INS (insulin)
Diseases named in the same sentence as INS in open-access papers (continued):
Sharing a sentence is not in itself a finding about the gene and the disease.
diabetes (continued). "The cAMP signaling-dependent mechanisms, mediated by cAMP-response element-binding protein (CREB), have been identified to play a critical role in improving insulin secretion and β-cell survival in diabetes." (PMID 34890851, 2022). "Seven patients (32%) had type 2 diabetes mellitus, merely 1 (14%) was insulin-dependent and 6 (86%) were treated with only oral antidiabetic therapies, mostly metformin." (PMID 33094471, 2022). "The development of drugs that target the relevant signaling pathway of PDX-1 in insulin regulation is crucial for diabetes treatment." (PMID 36551213, 2022). "NC, as well as neck ratios, have been strongly associated with insulin levels, HOMA-IR, lipid alterations and diabetes." (PMID 36501189, 2022). "Type 2 Diabetes Mellitus (T2DM) is a disorder characterized by defective insulin secretion or insulin resistance." (PMID 36547924, 2022). "Insulin resistance is the primary cause of type 2 diabetes mellitus and the presence of the G allele in PPARG Pro12Ala improves insulin sensitivity." (PMID 35265101, 2022). "Further advances in diabetes technology have led to the incorporation of glucose‐responsive algorithms which utilise sensor glucose data to adjust insulin delivery." (PMID 35642299, 2022). "Fruit juices with low GI are a healthier choice for people with diabetes as well as individuals who want to stay healthy since it produces more subtle postprandial glucose and insulin responses." (PMID 35227323, 2022). "Physical activity leads to reduced inflammatory pathways that improve the development of insulin and leptin resistance, abdominal obesity, atherosclerosis, neurodegeneration, Type 2 diabetes mellitus, dementia, and cardiovascular disease." (PMID 35743182, 2022). "Kenowitz et al27 also found that people with diabetes with high self-esteem had better compliance with their insulin treatments and exercise schedules." (PMID 36261206, 2022). "Serum ADAM10 was increased in subjects with diabetes compared with control (40.5 ng/mL [22.3‐65.7] vs 10.3 ng/mL [7.0‐17.9], respectively; P < .01); the highest levels were seen in insulin‐treated subjects." (PMID 35705192, 2022). "In 2003, Kahn (2003) demonstrated the specific contribution of both insulin resistance and beta-cell dysfunction to the pathogenesis of diabetes, laying a foundation for the basic pathological mechanisms of such disease." (PMID 35721855, 2022). "Housebound patients with diabetes needing support with insulin—a project to improve service standards." (PMID 35983585, 2022). "The LADA diagnosis is considered to apply to a subgroup of individuals with autoantibodies who initially present with diabetes similar to type 2 diabetes, but subsequently require insulin." (PMID 35953726, 2022). "Diabetes mellitus is a state of chronic hyperglycemia due to the insufficient secretion of insulin that results an impaired uptake of blood glucose." (PMID 36443433, 2022). "For most patients with diabetes mellitus, despite improvements in insulin replacement therapy, reduced bone mass and low bone mineral density are observed." (PMID 35730406, 2022). "Multiple daily injections of insulin, self-monitoring of blood glucose, prevention of acute and chronic complications, structured diabetes education, psychosocial support, and safe disposal of sharps are essential components in the management of T1DM." (PMID 37384263, 2022). "Diabetes mellitus (DM) is a chronic multisystem disorder influenced by a complex interaction of genetic, socioeconomic, and behavioral factors that impair insulin secretion from the pancreas resulting in insulin resistance." (PMID 35755551, 2022). "Despite the fact that only 23.6% of persons were diagnosed with diabetes, obese patients needed greater amounts of fasting insulin and C-peptide to maintain normal blood glucose levels." (PMID 36686491, 2022).
diabetes (continued). "For example, one study investigating sex differences in a high-fat diet-induced diabetes model found an interaction between diet and insulin levels modulated by the stress receptor Crhr2." (PMID 35883660, 2022). "Oxidative stress can impair insulin signaling pathways and induce cytotoxicity in pancreatic β-cells, leading to insulin resistance and diabetes." (PMID 35204166, 2022). "For this, our subtyping method can be used, which uses blood glucose and insulin response to a five-point OGTT as a measure of diabetes pathophysiology." (PMID 35327447, 2022). "The recommended insulin therapy scheme is the basal/bolus regimen by means of microinjective therapy or with insulin pump, similarly to what indicated in the guidelines for diabetes therapy in the general population." (PMID 35407442, 2022). "Long-term TTh in diabetic men resulted in progressive improvements in obesity and insulin requirements, including a substantial number who experienced complete remission of diabetes." (PMID 36643964, 2022). "Sensitivity analyses were performed to clarify the impact of previous diabetes mellitus and hypoglycemic treatment, including insulin injection and oral agents." (PMID 36699024, 2022). "For long-standing diabetes patients, a relatively low PDA risk population, insulin use is safe and long duration of insulin use is associated with a decreased PDA risk." (PMID 35252207, 2022). "Results: among residents, 21,190 people had diabetes, 2282 of whom were taking insulin; 1689 cancers occurred, 180 among insulin users." (PMID 35681699, 2022). "Individuals with diabetes are older and have disrupted insulin signaling, which is related to the pathophysiology of PD." (PMID 36008425, 2022). "Medical prescriptions related to diabetes are generally described as complex and burdensome (e.g., multiple injections of insulin, adaptation of insulin doses to different circumstances)." (PMID 35950071, 2022). "It is thought that genistein prevents diabetes by preserving insulin-positive β-cells and altering the hepatic glucose metabolic enzyme profile." (PMID 35203540, 2022). "In our study group, a significantly lower number of patients with severe renal dysfunction who needed dialysis (standardized difference = −0.14) and with diabetes treated with insulin (standardized difference = −0.10) were reported." (PMID 37669150, 2022). "Type 1 diabetes mellitus (T1D) is a chronic autoimmune disease in which destruction of the insulin-producing β-cells in the pancreatic islets requires regular lifelong insulin replacement therapy, the only lifesaving treatment available at this time." (PMID 35355800, 2022). "As β-cells play a predominant role in the development of both forms of diabetes, numerous β-cell lines that mimic various features of glucose-responsive insulin secretion have been established and/or engineered." (PMID 35600597, 2022). "Of all cases, 21 (12%) were treated with intravenous insulin for uncontrolled diabetes or diabetic ketoacidosis during hospitalization." (PMID 34586055, 2022). "Type 2 diabetes mellitus is regarded as resistance to insulin hormone which occurs because of attenuated signaling from the insulin receptors." (PMID 36875821, 2022). "Diabetes mellitus (DM) is a group of metabolic disorders characterized by hyperglycemia and insufficiency of either production or function of insulin." (PMID 35453355, 2022). "Diabetes is one of the fastest growing chronic diseases, characterized by hyperglycemia and glucosuria due to defects in insulin secretion and action." (PMID 36613249, 2022). "Additional research on the location and expression of IDO in pancreatic tissues showed that diabetes patients with new-onset or other autoimmune diseases had significantly lower levels of IDO expression in insulin-secreting islets." (PMID 36405706, 2022).
diabetes (continued). "In summary, administration of mulberry leaf powder extract in prediabetes and the early stage of diabetes can alleviate insulin resistance and inflammation and promote mitochondrial function in terms of energy production and fission." (PMID 36364802, 2022). "There is a growing awareness that perturbations in glucose/insulin metabolism can contribute to the development of AD, such that AD has been branded “diabetes of the brain”, and there is evidence supporting the anti-diabetic effects of probiotics." (PMID 35685773, 2022). "The high glycemic load had been documented to adversely affect insulin sensitivity, a well-established detrimental factor for diabetes." (PMID 35186834, 2022). "S and her mother came the next morning, prepared for a hospital stay of 4–5 days to learn about diabetes, insulin injection techniques, diet management, and other nitty-gritties." (PMID 35008043, 2022). "In elderly persons with type 2 diabetes basal insulin is recommended to simplify diabetes management, as basal insulin is easy to handle (e.g. pre-filled pen, injection only once daily) and has a low risk of inducing hypoglycemia." (PMID 36992745, 2022). "The oral glucose tolerance test (OGTT; 0′—105 mg/dL, 60′—232 mg/dL, 120′—217 mg/dL) performed during pregnancy revealed diabetes, so high-dose insulin therapy was administered." (PMID 35626278, 2022). "Several studies suggest that gut dysfunction can lead to diabetes by affecting glucose metabolism, triggering immunological responses, and increasing insulin resistance and low-grade inflammation." (PMID 36045662, 2022). "For example, a diabetes patient can only self-administer the correct insulin dosage if they know about the disease and insulin’s effect on their body." (PMID 36056354, 2022). "This year, 2022, marks the 100th anniversary of the isolation of human insulin and its administration to patients suffering from diabetes mellitus (DM)." (PMID 35454166, 2022). "Some people with diabetes reported feeling too sickly to attend work or school due to hyperglycemia from insulin rationing." (PMID 35436214, 2022). "In order to better understand type 2 diabetes pathophysiology, we also included other diabetes-related traits, including fasting glucose (FG), glycated hemoglobin (HbA1c), and fasting insulin (FI)." (PMID 35203577, 2022). "Diabetes mellitus (DM) is a group of metabolic disorders characterized by chronic hyperglycemia which results from defects in insulin secretion and/or insulin resistance." (PMID 35694215, 2022). "The VWF was significantly increased in insulin-requiring diabetes, which indicated diabetic endothelial injury and damage were the primary mechanisms contributing to an increased occurrence of vascular and cardiac events in diabetic postinfarction patients." (PMID 35966750, 2022). "According to the ADA recommendations, adolescents with type 1 diabetes should have a DSMES including MNT as part of diabetes care, with a physical activity program in addition of insulin therapy." (PMID 35459205, 2022). "It is worth noting that the children with diabetes in this study were primarily managed by insulin injection." (PMID 36508408, 2022). "Insulin resistance and compromised insulin secretion lead to impaired glucose metabolism, which contributes to the development of Diabetes." (PMID 35743160, 2022). "Metformin is a biguanide that is postulated to potentiate insulin sensitivity by inhibition of mitochondrial enzymes and is generally the first-line medical treatment for diabetes mellitus type 2." (PMID 34097240, 2022). "In settings where individuals are required to pay out-of-pocket for all or part of their diabetes care, which includes insulin as well as syringes, blood glucose meters, and the necessary health education, cost can make insulin treatment unaffordable." (PMID 35143780, 2022). "Other people with diabetes described alternative ways to access insulin, such as engaging in online insulin trading and seeking insulin donations." (PMID 35436214, 2022).
diabetes (continued). "Adherence to oral anti-diabetes and insulin in Iran has been shown to be comparable to that in Western countries." (PMID 37543884, 2022). "Nowadays, monomeric compounds have played an important role in the treatment of diabetes such as glimepirideas well as insulin." (PMID 36678522, 2022). "Hence, assessment of insulin sensitivity quantitatively may help in identification of patients at higher risk for metabolic sequelae like the development of diabetes and may also allow the selection of patients who are most likely to respond to treatment with insulin-sensitizing drugs." (PMID 37361870, 2022). "Differences in dietary intake exist among U.S. adults by insulin use and diabetes status using NHANES 2009–2016." (PMID 36014790, 2022). "The first trial in the ADAPT-T2D project is the Diabetes telemonitoring of patients in insulin therapy (DiaMonT) trial." (PMID 36476605, 2022). "For people with diabetes, injectable insulin treatment is a sign of their health’s severe deterioration." (PMID 36556420, 2022). "Diabetes is among the most common chronic illnesses, occurring when the β-cells in the pancreas are unable to produce enough insulin to properly manage the body’s blood sugar levels." (PMID 36251711, 2022). "Beans and whole grains are beneficial to people with diabetes because of high fiber and low glycemic index, making diabetics assist in maintaining healthy blood glucose and insulin levels." (PMID 35978964, 2022). "It is well known that the development of diabetes entails alterations in insulin-sensitive tissues such as the liver, the skeletal muscle, and the adipose depots, leading to a state of glucose intolerance." (PMID 35346213, 2022). "Gradually, by the late 20th century, as the mechanisms behind diabetes started to unfold, various insulin preparations and other oral hypoglycemic drugs paved their way onto the market." (PMID 35203540, 2022). "Standardized fecal bacterial transplantation decreases insulin resistance and improves insulin sensitivity, thus arresting the progress of type 2 diabetes mellitus (T2DM)." (PMID 36081798, 2022). "Most treated diabetes patients take oral medications or insulin injections, control diet, monitoring blood glucose, and the percentage of increased exercise was relatively low." (PMID 35457673, 2022). "Diabetes management requires certain responsibilities from patients, which includes honouring medical appointments, adherence to medication or insulin, glucose monitoring, healthy eating and increased physical activity." (PMID 36564779, 2022). "Real-time FGM with visible blood glucose improves daily glycemic control and diabetes self-care behaviors better than retrospective FGM in patients with type 2 diabetes on premix insulin therapy." (PMID 35222287, 2022). "A bio-guided fractionation study aimed for the isolation of active components of Tinospora crispa Miers (Menispermaceae) traditionally used for the treatment of diabetes through the activation of insulin signalling." (PMID 36080269, 2022). "Flavonoids and phenolic compounds are found to have several benefits against many disorders, including diabetes, by targeting different pathways and affecting β-cell proliferation, as well as insulin signaling and secretion." (PMID 36588726, 2022). "Typically, adolescents, I would say... don’t manage their diabetes, don’t take their insulin, measure blood glucose." (PMID 36011214, 2022). "Type 2 diabetes mellitus (T2D) is a multifactorial and heterogeneous metabolic disorder characterized by a higher glucose level due to insufficient insulin production, action, or both." (PMID 36101450, 2022). "According to the researchers, antioxidants play an important role in preventing complications of diabetes and recovering insulin sensitivity by protecting the β-cell against apoptosis that occurred during oxidative stress." (PMID 36557305, 2022).
diabetes (continued). "This review found evidence of the negative association between SB and fasting 2-h glucose, fasting insulin, 2-h insulin, incident diabetes and IL-6." (PMID 35544519, 2022). "Here, we focus on discussing human induced pluripotent stem cell (hiPSC)‐derived insulin‐producing β cells as the commercial therapeutic product for diabetes treatment." (PMID 35474596, 2022). "Untreated insulin resistance leads to diabetes, with insulin resistant people needing larger amounts of insulin to transport glucose into their cells." (PMID 36613051, 2022). "Clinical studies have found that among the antidiabetics, metformin, insulin, pioglitazone, sitagliptin, and other drugs can significantly improve the cognitive ability of diabetes patients." (PMID 39280108, 2022). "Diabetes mellitus (DM) is a serious, chronic metabolic condition characterized by a state of hyperglycemia resulting from defects in insulin secretion, insulin action, or both." (PMID 36525442, 2022). "Stress-induced impaired insulin function is one of the major factors of hyperglycemia in TBI patients besides diabetes." (PMID 35968315, 2022). "The gene enrichment analysis (GEA) retrieved by using the STRING database revealed that most of these genes were correlated with FoxO, cytokine, and AMPK signaling, diabetes, and insulin sensitivity." (PMID 36360783, 2022). "These biological pathways include, for example, apoptosis pathway, an inflammatory response pathway, senescence and autophagy pathways, insulin signaling pathway, type 1 diabetes mellitus pathway, and type 2 diabetes mellitus pathway." (PMID 35327520, 2022). "Smokers are also more likely to experience severe hypoglycemia and have difficulties with insulin dose adjustment and diabetes control." (PMID 36293800, 2022). "Diabetes mellitus (DM) is a chronic disease characterized by high blood glucose levels due to ineffective insulin production or utilization." (PMID 36055403, 2022). "Among the IGT participants, progress to diabetes (aHR = 2.28, 95%CI 1.24–4.20, P = 0.008) and insulin-area under the curve at baseline (for 1 SD increase, aHR = 1.39, P = 0.02) were also associated with the risk of cancer after adjustment of covariables." (PMID 35256755, 2022). "Diabetes mellitus is characterized by metabolic dysfunction resulting from changes in insulin secretion and/or resistance to its actions." (PMID 35453417, 2022). "Among adults using insulin for their diabetes treatment, the current mean age was 60.6 years (95% CI, 59.2-61.9 years) and did not change significantly over time (P = .39 for trend)." (PMID 36538330, 2022). "Defective insulin signaling in mouse models of diabetes or the genetic disruption of the insulin signaling pathway in podocytes propagates hyperglycemia induced maladaptive UPR and DN." (PMID 35455399, 2022). "The pharmacological control of diabetes is another complex topic, since dialysis treatment affects glucose and insulin levels and increases insulin sensitivity." (PMID 35329847, 2022). "With patients with diabetes, peer education resulted in increased self-care, better use of medication and reductions in the need for insulin." (PMID 35627601, 2022). "Barriers and facilitators to managing diabetes with insulin in people with intellectual disabilities were identified related to the individual, other people participating in their care, and broader environmental and social factors." (PMID 35983585, 2022). "Other people with diabetes described difficulty managing blood glucose when using generic insulin (regular and neutral protamine hagedorn) compared with brand-name insulin." (PMID 35436214, 2022). "The use of strictly managed glycemic control strategy can reduce blood glucose levels, insulin resistance levels in patients with AIS diabetes mellitus." (PMID 36060656, 2022).